TMEM42 (transmembrane protein 42)
Synonyms: MGC29956
Tractability: Antibody: UniProt predicts a signal peptide or a membrane-spanning region.
Gene: Protein-coding gene on chromosome 3 (44,861,889 to 44,865,670, forward strand). Ensembl gene ENSG00000169964.
Subcellular location: Membrane
Subcellular location (Human Protein Atlas): Nucleoplasm; Nucleoli
Gene Ontology:
Molecular function: protein binding
Cellular component: membrane
Genetic constraint (gnomAD): Loss-of-function variants: 8 observed, 14.12 expected, observed/expected ratio (o/e) 0.57, 90% interval 0.33 to 1.02. The synonymous counts are far from expectation, so gnomAD's model fits this gene poorly and the ratio says little. Missense variants: 211 observed, 185.51 expected, observed/expected ratio (o/e) 1.14, 90% interval 1.02 to 1.27. Synonymous variants: 115 observed, 83.82 expected, observed/expected ratio (o/e) 1.37, 90% interval 1.18 to 1.6.
Homologues: Orthologues: chimpanzee TMEM42 (99% identical), rabbit TMEM42 (89% identical), dog TMEM42 (86% identical), guinea pig TMEM42 (86% identical), pig TMEM42 (82% identical), mouse Tmem42 (81% identical), zebrafish tmem42a (34% identical), zebrafish tmem42b (30% identical), Drosophila melanogaster CG42495 (19% identical), Caenorhabditis elegans F40F8.3 (18% identical).